AFP (alpha fetoprotein)
Diseases named in the same sentence as AFP in open-access papers (continued):
Sharing a sentence is not in itself a finding about the gene and the disease.
liver cancer (continued). "The clinicopathological analysis demonstrated that high expression of DNMT1 protein was closely correlated with younger age (p = 0.017), high AFP level (p = 0.011), tumor venous invasion (p < 0.001), and a high BCLC (the Barcelona Clinic Liver Cancer staging) stage (p = 0.001) with the χ2 test." (PMID 35092191, 2022). "Previously, we demonstrated that AFP is not just a tumor marker but also reflects liver cancer stem cell features with a poor survival outcome." (PMID 35955438, 2022). "We compared and analyzed the diagnosis rate of liver cancer with four new markers by classifying patients with higher values as positive and negative below the AFP cut-off value (20 ng/mL) in the ELISA test." (PMID 35456219, 2022). "Gemcitabine and L-OHP + EPI + irinotecan + 5-FU, L-OHP + EPI, and L-OHP + irinotecan + EPI were more effective against AFP-positive compared with AFP-negative liver cancer cells according to in vitro high-throughput drug sensitivity screening." (PMID 35127582, 2022). "In addition, the levels of serum AFP and CA199 in the liver cancer group were significantly higher than those in the benign lesion group and the control group (P < 0.01)." (PMID 35237392, 2022). "Although 30%–40% of primary liver cancer is negative for AFP, it is still a sensitive tumor marker for the detection of HCC and a useful predictive factor due to its specificity for patient survival after locoregional or systemic treatment in HCC." (PMID 34336647, 2021). "In conclusion, the comprehensive use of serum biomarkers is a promising method to predict the development of HCC, especially early and AFP-negative liver cancer." (PMID 34722278, 2021). "The alpha-fetoprotein (AFP) is an acidic glycoprotein synthesized from yolk sac and liver cells in embryo and is currently the most sensitive marker for the diagnosis of primary liver cancer." (PMID 34527571, 2021). "Alpha-fetoprotein (AFP) is a single-stranded serum glycoprotein, an important biomarker commonly used in the clinical diagnosis of HCC, it is a specific protein with high expression during the occurrence of liver cancer." (PMID 34976809, 2021). "Considering the uncertainty of AFP function in the tumorigenesis and progression of HCC cells, whether it can be used as a therapeutic target for liver cancer is controversial." (PMID 34680245, 2021). "In particular, we revealed a 3-RNA detection panel for liver cancer patients, especially AFP-negative patients and those with early-stage cancer." (PMID 33391469, 2021). "Likewise, serum AFP, CEA, and CA19-9 levels were significantly increased in PLCs relative to healthy controls, indicating that TrxR activity and AFP, CEA, and CA19- are potentially sensitive biomarkers for liver cancer before clinical intervention." (PMID 33727662, 2021). "Numerous glycoproteins have been confirmed to screen AFP-negative liver cancer in clinical studies, including Golgi protein 73 (GP73), dickkopf-1 (DKK1), angiopoietin-like protein 2 (ANGPTL2), and haptoglobin (Hp)." (PMID 33889548, 2021). "The selected 3-RNA panel successfully detected 79.2% AFP-negative samples and 77.1% early-stage liver cancer samples in the testing and validation sets." (PMID 33391469, 2021). "This study has clarified the existence of potential biomarkers, such as the two glycopeptides of PON1 in AFP-negative liver cancer." (PMID 33889548, 2021). "AFP was detected in only 1% of the cells suggesting that the cells are still undifferentiated as liver cancer cells independent of Nanog expression." (PMID 32203212, 2020). "The mechanisms leading to aberrant expression of AFP in liver cancer and other types of tumors are not clear yet." (PMID 31897235, 2020). "Despite numerous studies and the introduction of numerous biomarkers, it seems that a specific biomarker that has the ability to detect liver cancer early along with AFP has not been introduced yet." (PMID 33585001, 2020).
liver cancer (continued). "In C3H-background mice, we demonstrated that depleting AFP did not affect liver cancer initiation but suppressed tumor progression." (PMID 33009373, 2020). "Imaging examinations (e.g., ultrasound imaging (UI), computer tomography (CT) imaging, and magnetic resonance imaging (MRI)) and serum measurements (e.g., alpha-fetoprotein (AFP) and glypican-3 (GPC3)) are the most commonly used methods for early screening and diagnosis of liver cancer." (PMID 32293343, 2020). "Notably, high expression of Nek2 in HCC was significantly correlated with alpha-fetoprotein (AFP, P = 0.028), tumor size (P = 0.02), Barcelona Clinic Liver Cancer stage (BCLC stage, P = 0.031), and local relapse (P = 0.034)." (PMID 31319849, 2019). "In addition, the IMF deposition group showed higher AFP, INR, and CP score, and lower sodium and albumin levels, which are markers of the severity of liver cancer." (PMID 31888500, 2019). "Given the high false positive rates inherent in imaging-based liver cancer screening and the high false negative rate of blood AFP protein-based liver cancer detection, it is essential to develop accurate, affordable and minimally invasive assays." (PMID 29879168, 2018). "We found that GSTP1 could decrease p-Akt in liver cancer cell lines, and speculated that GSTP1 may inhibit AFP expression." (PMID 29507666, 2018). "Univariate analysis shows that Barcelona Clinic Liver Cancer (BCLC) classification stage (p = 0.001), HBsAg positive (p = 0.003), AFP levels > 400 ng/ml (p = 0.033), tumor size (p = 0.002) and Vascular invasion (p = 0.028) were significantly influence tumor-free survival time." (PMID 28903351, 2017). "AFP is a the gold standard tumour marker for HCC and its expression is upregulated during hepatocarcinogenesis, hence the use of AFP as a standard biomarker of liver cancer screening." (PMID 29268718, 2017). "Barcelona Clinic Liver Cancer (BCLC) stage and alpha fetoprotein (AFP), aspartate aminotransferase (AST), gamma-glutamyl transferase (GGT), lactate dehydrogenase (LDH), alkaline phosphatase (ALP), and albumin (ALB) levels differed between the SIRI < 1.05 and SIRI ≥ 1.05 groups." (PMID 28430597, 2017). "In a univariate analysis, Barcelona Clinic Liver Cancer (BCLC) stage C (P < 0.001), α-fetoprotein (AFP) level ≥400 ng/mL (P = 0.019), tumor size ≥10 cm (P = 0.023), extrahepatic metastases (P = 0.002), and portal vein tumor thrombosis (P < 0.001) significantly correlated with poor overall survival." (PMID 29108296, 2017). "We found thatBITC inhibited viability, migration, invasion and induced apoptosis of human liver cancer cell lines, Bel 7402(AFP producer) and HLE(non-AFP producer) cells in vitro." (PMID 27716619, 2016). "Moreover, prolonged MB109 treatment suppressed the expression of five prominent liver cancer stem cell (LCSC) markers, including CD44, CD90, AFP, GPC3 and ANPEP." (PMID 27650540, 2016). "However, AFP and CEA have a much lower specificity than des-γ-carboxyprothrombin (DCP) to detect liver cancer." (PMID 26610504, 2015). "Furthermore, AFP and PIVKA-II also had specific relationships to liver cancers (50.0% and 50.0%, respectively)." (PMID 26115010, 2015). "It appears that liver cancers with Gls2 promoter methylation were found to have higher percentage of abnormal AFP and higher TNM stage, although no statistical differences were found, probably due to the relative small sample size." (PMID 24330717, 2013). "Nevertheless, AFP levels are often elevated in some patients with chronic liver disease who do not have cancer, and AFP levels are not elevated in 30–40% of patients with liver cancer." (PMID 22808038, 2012). "Generally speaking, if an individual has an elevated level of AFP, a search for testicular or liver cancer will be made, but AFP has no known function in healthy human beings." (PMID 21573244, 2011).
liver cancer (continued). "While our study demonstrated that elevated AFP levels are a strong marker for distinguishing primary liver cancer from liver metastases, we did not evaluate the dynamic changes in AFP levels during treatment and their potential correlation with disease prognosis." (PMID 39857748, 2025). "Furthermore, the “Compound CTD Capsule” could reduce alpha-fetoprotein (AFP) levels and improve survival rates in patients with advanced primary liver cancer." (PMID 41339928, 2025). "According to the Barcelona Clinic Liver Cancer (BCLC) classification, 3 patients were stage A, 65 were stage B, and 79 were stage C. Regarding tumor markers, the median AFP level was 50.1 ng/mL (range, 1.8–2,037,310), and 96 patients (65.3%) had AFP ≥ 10 ng/mL." (PMID 41463142, 2025). "However, current clinical features and biomarkers, such as the TNM staging system, Barcelona Clinic Liver Cancer (BCLC) staging system, and serum alpha-fetoprotein (AFP) level, are insufficient for providing accurate prognostic evaluations for HCC patients in clinical practice." (PMID 39660866, 2025). "AFP, used in liver cancer diagnostics, can be elevated in chronic hepatitis, liver cirrhosis, and even pregnancy, as liver cell regeneration in non-cancerous liver diseases also elevates AFP levels." (PMID 39639411, 2024). "By combining AFP with other relevant biochemical markers, such as circulating tumor cells, tumor markers other than AFP (e.g., carcinoembryonic antigen, CA19-9), and specific gene expression profiles related to liver cancer, a more comprehensive and accurate predictive model can be developed." (PMID 39767676, 2024). "This suggests that the disease burden of liver cancer death is decreasing year by year, which is related to China's long-term effective neonatal HBV vaccination policy, the reduction of aflatoxin contamination in the diet, and alpha-fetoprotein screening in high-incidence areas." (PMID 38750424, 2024). "In multivariate analyses, female gender, diabetes, higher HCC-nonB ratios, smaller tumors, and levels closer to normal for glutamate transpeptidase and total bilirubin remained significantly associated with negative AFP and PIVKA-II in liver cancer (P < .05 for each)." (PMID 39432605, 2024). "For example, not all patients with liver cancer present elevated AFP levels, and false positives may arise in certain benign liver conditions." (PMID 39742265, 2024). "Previously, our group developed a blood‐based multi‐omics assay for liver cancer early detection, which integrated genomics hallmarks such as copy number aberration (CNA) and fragment size (FS) from shallow whole genome sequencing (sWGS) of cfDNA with the protein marker AFP." (PMID 39704423, 2024). "Elevated alpha-fetoprotein levels do not always indicate liver cancer." (PMID 38463849, 2024). "One possible explanation for the results may be that GPC3 is more effective than AFP in detecting early-stage liver cancer and is not correlated with tumor size." (PMID 37046471, 2023). "The 2022 updated Barcelona Clinic Liver Cancer strategy for prognosis prediction and treatment recommendation for HCC suggested evaluating prognosis according to the tumor burden and cancer-related symptoms, and defined by the AFP, albumin-bilirubin score, Child-Pugh, and MELD scores." (PMID 37239939, 2023). "However, in the liver morphology and pathological changes of rats, it was found that ATXP had a positive regulatory effect on the liver cancer rat model and had a regulation effect on ALT, AST, GGT, AFU, AFP, and liver GST-Pi protein expression in a liver cancer rat model." (PMID 37313461, 2023). "Therefore, DCP has no advantage in predicting the prognosis of liver cancer due to AFP, but is advantageous for early diagnosis." (PMID 35307694, 2022). "In 10%-30% of liver cancers with negative AFP test, the sensitivity and specificity of AFP-L3 were 41.5% and 85.1%, suggesting that AFP-L3 may potentiate the AFP test efficiency." (PMID 35401747, 2022).
liver cancer (continued). "However, the sensitivity and specificity of AFP in diagnosing liver cancer are not very satisfactory." (PMID 35397600, 2022). "In addition, serum tests can be used, such as alpha-fetoprotein (AFP), which might be raised in 70% of patients with liver cancer." (PMID 35547447, 2022). "The possible reason is that AFP is not universally expressed in all liver cancers." (PMID 36605219, 2022). "By the selected panel, 79.2% AFP-negative samples and 77.1% early-stage liver cancer samples were successfully detected in the testing and validation sets, which indicated the potential of exRNAs panel in the early diagnosis of liver cancer." (PMID 35180868, 2022). "A study found that high neutrophil–lymphocyte ratio (NLR) was associated with low AFP expression in patients with hepatitis B virus (HBV) related HCC, therefore, NLR could be a potential clinical marker of the pathogenesis of AFP negative liver cancer." (PMID 35461226, 2022). "Huh-7 cell line possessing the properties of being positive for AFP and negative for HBV and susceptible to HCV compared with other liver cancer lines can be applied to study the regulation mechanism of gene expression, metabolism, xenotransplantation animal models, and so on." (PMID 35401213, 2022). "Importantly, AFP, CA19-9, and CEA together could help diagnose asymptomatic patients with primary hepatic cancer." (PMID 35122196, 2022). "Therefore, when diagnosing liver cancer, the combined use of GPC3 and AFP may make the diagnosis more reliable." (PMID 34200243, 2021). "Our findings revealed a multi-RNA panel that could be used for the diagnosis of liver cancer, especially for alpha feto-protein (AFP)-negative and early stage patients." (PMID 33391469, 2021). "In order to evaluate the performance of the 3-RNA panel for AFP-negative patients, we used 8 AFP-positive (AFP > 400 ng/mL) liver cancer patients as a positive training set, as well as 26 HDs and 24 chronic hepatitis B (CHB) patients as a negative training set, to generate a random forest model." (PMID 33391469, 2021). "This was demonstrably useful for the detection of AFP-negative liver cancer." (PMID 34754704, 2021). "Similarly, the expression of AFP were significantly higher in liver cancer than non-tumor liver tissue (t-test: p = 3.78e-24)." (PMID 31897235, 2020). "However, AFP-negative hepatic cancer (ANHC) is not as easily diagnosed, as most ANHCs are early and small HCCs, often without typical imaging characteristics." (PMID 32923383, 2020). "Indeed, the AFP often leads to high rates of false positives and false negatives: About 30% of primary liver cancer patients are AFP negative." (PMID 31450698, 2019). "Furthermore, although expression of liver or liver cancer markers differs between primary HCC cells, eight cultures of primary HCC cells exhibited albumin and HepPar-1 expression in the cytosol as well as AFP and albumin mRNA expression." (PMID 29801504, 2018). "Low FBP1 expression was significantly correlated with alpha-fetoprotein (AFP) ≥ 20 ng/ml (P = 0.026), portal vein tumour thrombus (PVTT) (P = 0.020), satellite nodule (P = 0.006), advanced TNM stage (P = 0.001) and advanced Barcelona Clinic Liver Cancer stage (BCLC stage; P = 0.001)." (PMID 30429463, 2018). "However, AFP has limitations in the detection of liver cancer due to its lack of tumor specificity and sensitivity." (PMID 30065664, 2018). "The immunostains for intrinsic liver cancer markers AFP, Hep Par 1 and GPC3 were all negative." (PMID 28955934, 2016). "Hepatic cancer was visually observed by histopathological evaluation (hepatic cord thickening and hepatic portal triad disruption etc.)and by testing for the HCC marker AFP (α-Feto protein), which was >3.00 fold higher at both the transcript as well as protein level when compared to control mice." (PMID 27760163, 2016).
liver cancer (continued). "A study conducted by the liver cancer study group of Japan showed that 4.9 % (10/205) of all ICC patients had a serum AFP level more than 1000 ng/mL, 1 % (2/205) higher than 10,000 ng/mL, and only 0.5 % (1/205) of the ICC patients had a serum AFP level greater than 100,000 ng/mL." (PMID 27301956, 2016). "Interestingly, while among those HBsAg negative HCC patients, Barcelona Clinic Liver Cancer (BCLC) stage, INR value and Albumin (ALB) value, but not AFP value, were the independent risk factors affecting postoperative survival time." (PMID 26784252, 2016). "However, benign liver diseases can also cause an increase in blood AFP levels, and CEA is commonly used for screening several forms of cancer, not specifically liver cancer." (PMID 26610504, 2015). "Tumor markers such as alpha fetoprotein (AFP), carcinoembryonic antigen (CEA), cancer antigen 125 (CA125) and cancer antigen 19–9 (CA19-9) have been widely used for the diagnosis of different types of cancers such as liver cancer, colorectal cancer and pancreatic cancer." (PMID 23672279, 2013). "However, the specificity and sensitivity of AFP used in screening for liver cancer are not satisfactory." (PMID 24649215, 2013). "In addition to being present in three normal cell lines, SV40EAFP activity was observed in four AFP positive and two AFP negative liver cancer cell lines." (PMID 22040050, 2011). "However, 30% of patients with liver cancer do not exhibit high AFP levels." (PMID 38968748, 2024). "However, approximately 30% of patients with liver cancer are always negative for serum AFP." (PMID 37189543, 2023). "Previous studies in our laboratory have shown that AFP could induce the expression of downstream target genes by activating the PI3K/Akt signaling pathway and regulating the growth, proliferation, invasion, metastasis, generation of stem cells, and other malignant behaviors of liver cancer cells." (PMID 36911723, 2023). "Further more, some studies have found that the sensitivity of MDK for the diagnosis of HCC could reach 85% through meta-analysis, and other studies have shown that the sensitivity can reach more than 80% in the early stages of liver cancer and AFP-negative liver cancer." (PMID 37193028, 2023). "MR Analysis of air pollution and primary liver cancer related tumor markers AFP, OPN and GPC-3 found no causal association, further confirming our previous conclusion that there was no statistical association between air pollution and primary liver cancer risk." (PMID 37575092, 2023). "Compared with AFP (positive likelihood ratio: 0.206 and negative likelihood ratio: 0.985), both RRM1 and RRM2 had greater positive likelihood ratios and less negative likelihood ratios, suggested that they might have a great diagnostic value for liver cancer." (PMID 36713030, 2023). "However, previous research has reported AFP negative cases in liver cancer patients and AFP overexpression in benign liver lesions, which suggests the unavailability of stand-alone diagnosis of early primary liver cancer using serum AFP." (PMID 35401747, 2022). "Studies have shown that tumor burden including tumor size and tumor number, biomarkers including AFP and NLR, post-treatment extent of disease (POST-TEXT) stages, tumor differentiation, vascular invasion, and chemotherapy could predict the prognosis of liver cancer patients undergoing LT." (PMID 36117822, 2022). "Considering the role of FOXM1 in proliferation and AFP expression in AFP-positive HCC cells, it is possible that the inhibition of FOXM1 with a very low concentration of carfilzomib might be therapeutically effective to suppress the proliferation of AFP-positive liver cancer stem cells." (PMID 35955438, 2022). "However, the sensitivity and specificity of AFP in the diagnosis of liver cancer is not ideal." (PMID 34660300, 2021).